VDR (vitamin D receptor)
Diseases named in the same sentence as VDR in open-access papers (continued):
Sharing a sentence is not in itself a finding about the gene and the disease.
sarcopenia (continued). "Previous research has linked some VDR polymorphisms with the reduction of muscle mass and function in the elderly, suggesting that vitamin D plays a role in the development and progression of sarcopenia." (PMID 25705670, 2015). "For example, both polymorphisms in the vitamin D receptor gene and low serum vitamin D levels have been implicated in sarcopenia and in increased myofibrillar protein degradation at younger ages, suggesting that polymorphisms in the vitamin D receptor probably lead to its partial inactivation." (PMID 24092876, 2013). "Therefore, we hypothesized that 1,25(OH)2D upregulates Sirt1 in myoblasts via VDR signaling and that Sirt1 overexpression in MSCs may prevent sarcopenia induced by 1,25(OH)2D deficiency." (PMID 40168539, 2025). "However, an increasing deficiency of VD and decreasing expression of VDR occur with ageing, which may lead to sarcopenia, and thus, individuals with sarcopenia have lower VD levels." (PMID 29387723, 2017). "The analysis incorporated international diagnostic criteria for sarcopenia (EWGSOP2, AWGS, FNIH, IWGS), current guidelines for Vit D sufficiency, and molecular mechanisms related to Vit D receptor (VDR) signaling in muscle tissue." (PMID 40868119, 2025). "Recent studies have highlighted the potential role of vitamin D receptor (VDR) in sarcopenia and muscle health." (PMID 38004107, 2023). "Like VDR, the age-related decline in protein deacetylase sirtuin (SIRT) expression is linked to the development of sarcopenia and age-related muscle dysfunction." (PMID 38004107, 2023). "Allelic variations in CYP2R1 (rs10741657), GC (rs2282679), and VDR (rs10741657) affect vitamin D levels and decisively influence the degree of sarcopenia in institutionalized elderly people." (PMID 36233147, 2022). "In this study, we investigated the connection between CYP2R1 (rs10741657), GC (rs2282679) and VDR (rs2228570) on serum 25-OH/D concentrations and the relationship to the degree of sarcopenia in institutionalized elderly people." (PMID 36233147, 2022). "Concerning to VDR SNP rs228570 the institutionalized seniors recognized with sarcopenia were 2 for AA, 3 for GA and 5 for GG." (PMID 36233147, 2022). "The proposed mechanism seems to indicate that sarcopenia is related to a decrease in vitamin D receptor in muscle, leading to a reduction in post-exercise recovery." (PMID 34579009, 2021). "VDR is one of the most frequently studied candidate genes for sarcopenia, due to its crucial regulatory role in calcium homeostasis and the skeletal muscle function." (PMID 34680417, 2021). "The vitamin D receptor (VDR) is one of the candidate genes for sarcopenia, because it plays an important regulatory role in calcium homeostasis and skeletal muscle function." (PMID 33505434, 2020). "One of the most widely studied candidate genes for sarcopenia is Vitamin D receptor (VDR), due to its key regulatory role in calcium homeostasis and skeletal muscle function." (PMID 30574409, 2018). "Overall, our data highlight the prominence of VDR activity and genetic variability on muscle aging and sarcopenia typical of OA and OP patients." (PMID 30574409, 2018). "In practice, VD supplementation increases the expression of VDR in skeletal muscle, which blocks the development of sarcopenia." (PMID 29387723, 2017). "Experimental tests in a mouse model have shown that VDR is important for the reduction of lean mass, sarcopenia, reduced grip strength and physical performance, confirming that the vitamin D-VDR interaction plays an important role in the physiology of skeletal muscle." (PMID 41226798, 2025). "These revealed an association between ACTN3 and VDR gene variants and sarcopenia, while no such association was observed for IL6 variants and a specific MSTN variant linked to strength in athletes." (PMID 40772803, 2025).
sarcopenia (continued). "In addition, it provides experimental evidence that vitamin D has the potential to be developed as a therapeutic or preventive agent against sarcopenia through the stimulation of the VDR/SIRT1/SIRT3 axis." (PMID 38004107, 2023). "Against this background, we set out to conduct a study on institutionalized elderly, to evaluate the impact and presence of a possible connection between CYP2R1 (rs10741657), GC (rs2282679), and VDR (rs2228570), serum 25-OH/D concentrations and the link with the degree of sarcopenia in older adults." (PMID 36233147, 2022). "Numerous epidemiological studies have revealed that vitamin D3 supplementation is able to improve muscle strength and physical performance in sarcopenia or elderly patients, but the mechanisms have remained unclear, especially since VDR expression is low in adult skeletal muscles." (PMID 35411556, 2022). "Future strategies targeting vitamin D signaling in muscle and modulating the VDR “metabolome” may also hold important clues for future treatments of musculoskeletal disorders, congenital myopathies, and sarcopenia." (PMID 34950830, 2021). "Our findings indicate that VDR genotypes can affect muscle traits and sarcopenia." (PMID 32696506, 2020). "Therefore, we focused on the determination of the single and combined effect of MTHFR, ACTN3, NRF2, VDR FokI, ADRB2, and NPAS4 polymorphism associated with sarcopenia in older adults." (PMID 33505434, 2020). "Therefore, the study of VDR in muscle tissue not only provides new insights into muscle physiology but also offers important therapeutic implications in the context of muscle disorders, sarcopenia, and physical rehabilitation." (PMID 40868119, 2025). "Moreover, vitamin D receptor (VDR) loss-of-function C2C12 myoblasts display severely compromised mitochondrial function, whereas muscle-specific VDR knock down in rodents leads to decreased expression of mitochondrial genes and sarcopenia." (PMID 35276842, 2022). "We could not detect any association of the VDR FokI genotype with strength or sarcopenia in our cohort." (PMID 33505434, 2020). "However, this study did not investigate the expression of VDR in muscle tissues and the association between VDR expression levels and frailty/sarcopenia." (PMID 33322706, 2020). "The most frequently mentioned genes correlated with the occurrence of sarcopenia include ACTN3, ACE and VDR, although in general, the list is more extensive, e.g., in the 54 studies of adults aged > 50 years, 26 genes and 88 DNA polymorphisms were analysed." (PMID 34680417, 2021). "On the other hand, genetic factors reported as sarcopenia biomarkers have also been identified such as angiotensin I-converting enzyme I (ACE), myostatin (MSTN), alpha actinin 3 (ACTN3), ciliary neurotrophic factor (CNTF), vitamin D receptor (VDR), insulin-like growth factor 1 (IGF1), and IL-6." (PMID 39194921, 2024). "Vitamin D receptor (VDR), which might be expressed in muscle fibers through vitamin D signaling, acts a crucial role in regulating myoblast proliferation, differentiation and moderate sarcopenia." (PMID 35271662, 2022). "Therefore, the potential reduction of VDR protein expression during sarcopenia that occurs in very old age should not be excluded." (PMID 32427932, 2020).
depression (35 papers, 2013 to 2026). "The association of these genotypes with penetrating behavior in CD is further demonstrated in patients carrying the haplotype AA/BB/tt in the VDR gene, a haplotype that has also been associated with other diseases, such as depressive disorders." (PMID 39458479, 2024). "As expression and nuclear activation of the VDR are necessary for the effects of vitamin D. It would be valuable to analyze in the future the possible association of all these polymorphisms with depression and suicide." (PMID 37049606, 2023). "They found no statistical association between the nine genotypes of BsmI, ApaI, and TaqI and the risk of developing major depression, but the BsmI-ApaI-TaqI TAC (BAt) haplotype of the VDR gene increased susceptibility to major depression." (PMID 37404714, 2023). "Numerous studies have investigated the association between five SNPs in the VDR gene and depression." (PMID 37404714, 2023). "Because the hippocampus is vital in the causes of depression, discovering VDR within it has encouraged many researchers to investigate the effects of vitamin D on hippocampal shape and function in animals." (PMID 35637805, 2022). "The VDR is found in dopaminergic neurons in the substantia nigra, prefrontal cortex, and hippocampus of humans and rats, all of which are linked to depression." (PMID 35637805, 2022). "The VDR, which functions as a gene regulator, has been found in several brain regions implicated in depression." (PMID 32244496, 2020). "Vitamin D receptor (VDR) is located in an important area of the brain associated with depression and emotional behavior, such as cingulate gyrus, hippocampus, thalamus, hypothalamus, and substantia nigra." (PMID 30728786, 2018). "Another major finding here is that VDR variants ApaI (AA) and Cdx2 (AA) interacted with dietary vitamin D to modify likelihood of depression." (PMID 24699387, 2014). "Furthermore, vitamin D influences inflammatory pathways that have been associated with depression by activating anti-inflammatory pathways through VDR-mediated gene transcription and downregulating autoimmune mechanisms that produce proinflammatory cytokines." (PMID 37242183, 2023). "Additionally, VDR was found in the prefrontal cortex and parts of the limbic system, and these brain areas had been implicated in the pathophysiology of depression." (PMID 33189154, 2020). "Next to these genes that may influence 25(OH)D status, associations between 25(OH)D and depression may also be modified by the efficiency of the vitamin D receptor (VDR), which has been identified in brain tissue." (PMID 26141257, 2016). "Because of the widespread presence of vitamin D receptor in areas of the brain including the hippocampus which is associated with the development of depression, it could be speculated that there is a clinical effect of vitamin D on depression." (PMID 23927040, 2013). "The widespread distribution of vitamin D receptors (VDR) and activating enzymes, along with 1,25-dihydroxyvitamin D3 (1,25(OH)2D3), regulates the expression of neurotrophic substances, affects neuron-related processes, and is associated with the onset of depression." (PMID 40821024, 2025). "Vitamin D receptors (VDR) and the enzymes required for local vitamin D activation are expressed in the brain and there are plausible biological mechanisms that could mediate an effect of vitamin D deficiency to depression." (PMID 33396887, 2020). "Neurons and glial cells express VDR and vitamin D-metabolizing enzymes in various regions, such as the prefrontal cortex and hippocampus, suggesting a possible role for vitamin D in depression and anxiety disorders." (PMID 35806075, 2022). "In support of this notion, it must be kept in mind that VDR and vitamin D are widely detected in several areas relevant to depression in the human brain." (PMID 36144231, 2022).
depression (continued). "Although several polymorphisms, including ApaI, of the VDR gene have been described, their effects on VDR function and interaction with severity of depression are still poorly understood." (PMID 32191745, 2020). "Several single nucleotide polymorphisms (SNPs) of the vitamin D receptor (VDR) have been observed in association with susceptibility to various pathologies, including autism, major depression, age-related changes in cognitive functioning, and Parkinson’s and Alzheimer’s diseases." (PMID 39062692, 2024). "There is currently no study on the relationship between VDR gene polymorphic variants and anxiety/depression symptoms in nonclinical patients and the response of cell lines to vitamin D treatment." (PMID 39062692, 2024). "First, VDR and 1-α-hydroxylase (vitamin D activating enzyme) are widely distributed in the brain, especially in the hippocampus, which plays a key role in the mechanisms of depression." (PMID 38201927, 2023). "Moreover, it is pertinent that in vitro studies clarify the role of VDR in the brain and the possible increase in its expression in case of depression or suicide." (PMID 37049606, 2023). "Most studies on the quality of life in patients with PBC or AIH addressed relations between specific aspects of disease, such as fatigue, pruritus, depression, and quality of life after liver transplantation but not the impact of VDR gene polymorphisms." (PMID 32727130, 2020). "Furthermore, dysregulation of vitamin D/VDR signaling contributes to neuroinflammation and impaired neuroplasticity in MDD, while certain VDR genetic variants have been associated with an increased susceptibility to depression." (PMID 41479556, 2026). "Similarly, Xu and Liang (2021) showed that Vitamin D3/VDR signaling mitigates post-stroke depression by upregulating hippocampal BDNF, and Numakawa and Kajihara (2025) emphasized that impaired BDNF–TrkB signaling is a hallmark of depression, schizophrenia, and neurodegeneration." (PMID 41226472, 2025). "Another study of survival and health effects in people over 90 years old showed that carriers of VDR rs2228570 A/A and/or G/A had little effect on longevity but may affect a variety of pathophysiologically relevant functions, including a significantly lower prevalence of depression." (PMID 37404714, 2023). "Rats exhibiting depression-like symptoms demonstrated increased expression of CYP27B1, CYP24A1 and VDR in the hippocampus and elevated levels of 1,25 (OH)2D." (PMID 37404714, 2023). "Finally, the lack of association between 25(OH)D and depression symptoms in our study could be attributed to different VDR genes in our setting or the complex interaction between vitamin D and both the serotonin transporter promotor gene polymorphism and childhood adversity experience." (PMID 35761369, 2022).
breast tumors (34 papers, 2005 to 2025). "Among human breast tumors, higher VDR expression is associated with decreased Ki-67 staining and better outcomes, with the lowest VDR expression often found in TNBC samples." (PMID 37583424, 2023). "Our current study provides insights into alternative methods of enhancing VDR with the bacterial product butyrate and probiotics, thus reducing the risk of breast tumors." (PMID 37074210, 2023). "The VDR-ApaI aa genotype was significantly associated with poorly-differentiated breast tumors (p = 0.04) in combined Cases." (PMID 23554871, 2013). "Further study is needed to show whether microbiota transplants can affect breast tumors in intestinal VDR-deficient mice that were previously germ-free." (PMID 37074210, 2023). "Genetic variants in the VDR gene may decrease the levels of VDR expression and increase the risk of breast tumors." (PMID 32986367, 2020). "In recent years, an increasing number of clinical studies have suggested that an optimal vitamin D status has a protective effect against BC development and that high Vitamin D receptor (VDR) expression in breast tumors is associated with a better survival rate." (PMID 28632174, 2017). "Breast tumors show decreased levels of VDR expression, which may be due to genetic variants in the VDR gene." (PMID 26517870, 2015). "Increased VDR expression was confirmed by the IHC staining of breast tumor tissues of VDRΔIEC mice with probiotic treatment." (PMID 37074210, 2023). "In the probiotic-treated VDRΔIEC mice, we found that probiotic treatment significantly restored the protein expression of VDR and reduced p-β-catenin (Ser552) in breast tumors." (PMID 37074210, 2023). "In VDRΔIEC mice, we observed significant downregulation of VDR at the protein level in breast tumor tissue." (PMID 37074210, 2023). "This is an obvious limitation of the present study, and future studies are needed to establish possible associations between vitamin D supplementation and vitamin D levels at the time of diagnosis with VDR status in breast tumors." (PMID 36014861, 2022). "Breast tumor tissues stained for VDR ‘almost exclusively’ as compared to their surroundings; invasive tumors showing more intense expression of VDR and more nuclear-centred, in situ tumors with cytoplasmic staining." (PMID 34638264, 2021). "Collectively, the TCGA data indicate that VDR High and VDR Low breast tumors are molecularly distinct, although both subsets of patients exhibit poorer survival than patients whose tumors express VDR in the normal range." (PMID 34950835, 2021). "As breast tumor progresses, expression of VDR is lost, implicating a profound role in breast tumor initiation." (PMID 34771496, 2021). "Based on these genomic data, expression of the genes that encode VDR, CYP27B1, and CYP24A1 appears to be in the normal range for the vast majority of breast tumors." (PMID 34950835, 2021). "Surprisingly, few human breast tumors (5%) displayed genomic alterations in VDR, and most of the alterations that were detected were amplifications." (PMID 32774770, 2020). "In the present study, immunohistochemical staining of VDR was performed on over 700 primary, invasive, breast tumors from the Malmö Diet and Cancer Study (MDCS)." (PMID 31358030, 2019). "On the other hand, Santagata and colleagues compared 3,157 human breast tumors to normal cell types and divided them into four major subtypes that were differentiated by ER, androgen receptor (AR), and vitamin D receptor (VDR) status." (PMID 29707142, 2018). "As one of the nuclear receptor (NR) members, VDR is found in both normal breast tissue and breast tumors." (PMID 28632174, 2017). "VDR-knockout mice exhibit excessive mammary epithelial proliferation and impaired apoptosis, and breast tumors with higher VDR expression are correlated with better patient prognosis." (PMID 24244740, 2013). "TN breast tumors expressed significantly lower VDR (76.4±6.2%) and higher CD44 (105.6±8.7%) expression compared to ER+ tumor groups." (PMID 23341935, 2013).